TOX3 (TOX high mobility group box family member 3)
Diseases named in the same sentence as TOX3 in open-access papers (continued):
Sharing a sentence is not in itself a finding about the gene and the disease.
breast carcinoma (continued). "This indicated CYP19A1 as a potential indicator for the tumor-promoting role of TOX3 in breast cancer." (PMID 33716953, 2020). "TOX3, or TOX high-mobility group (HMG)-box protein group family member 3, has been previously identified as a breast cancer susceptibility gene in a large-scale genome-wide association study." (PMID 33716953, 2020). "An association study and subsequent GO/KEGG study found that SNP rs3803662 (TOX3) is an independent prognostic factor for breast cancer, and TOX3 was predicted to be involved in the pathogenesis of breast cancer." (PMID 33716953, 2020). "Overexpression of TOX3 promotes invasion and metastasis in breast cancer cells and enhances their invasive ability by downregulating BRCA1 expression, whereas tumorigenesis and tumor formation are significantly reduced after TOX3 downregulation." (PMID 33716953, 2020). "Collectively, this study aimed to explore the effect of TOX3 on estrogen synthesis from the perspective of estrogen production, in an attempt to link abnormalities in hormone production with the development of breast cancer." (PMID 33716953, 2020). "In the mammary glands of mice, TOX3 was found to be highly expressed during breast cancer, and its expression was correlated with clinical tumor, nodes, and metastases stage progression." (PMID 33716953, 2020). "The expression of TOX3 within the context of breast cancer is reported to be a potential tumor oncogene." (PMID 33716953, 2020). "In our work, TOX3 promoted estrogen biosynthesis by upregulating genes related to the development of breast cancer, including FSHR, CYP19A1, and BMP6." (PMID 33716953, 2020). "This study confirmed previous associations between increased breast cancer risk and SNPs in CASP8, TOX3 and ESR1." (PMID 31125336, 2019). "Taken together, both genetic and epigenetic factors play a role in TOX3 overexpression in breast cancer." (PMID 31757997, 2019). "Collectively, the expression of TOX3 has been correlated with breast cancer and is important in revealing biological mechanisms, which makes a bridge between pathways and diseases." (PMID 31338012, 2019). "rs3803662 on 16q12, located close to TOX3 (TNRC9, CAGF9) and LOC643714, has been identified as a breast cancer risk allele in various GWAS and linked to both ER-positive and ER-negative primarily postmenopausal breast cancer." (PMID 31125336, 2019). "The estimated increases in the risk of BRCAX or high-risk breast cancers from the variants on FGFR2, TOX3, and ESR1 were quite similar across populations (ORs for highest compared to lowest tertile = 2.2 to 2.4)." (PMID 30323354, 2018). "For example, a 2014 study showed association between breast cancer risk and seven breast cancer susceptibility loci (FGFR2, TOX3, STXBP4, SLC4A7, LSP1, 2q35, and 5p12)." (PMID 30249004, 2018). "To determine if epigenetic regulation of the TOX3 promoter contributes to the subtype-specific expression of TOX3, we performed bisulfite sequencing in breast cancer cell lines." (PMID 27806084, 2016). "The SNPs at 16q12, close to the TOX3 and CASC16 genes, represent one of the susceptibility loci identified by GWAS, showing strong evidence for breast cancer association across various populations." (PMID 27806084, 2016). "Our data also showed a 2.93±0.27 fold increase in TOX3 expression in 5-aza-CdR treated cells compared to control, indicating that CpG methylation of the TOX3 promoter plays a significant role in the regulation of TOX3 expression in the breast cancer cell line." (PMID 27806084, 2016). "We identified hypomethylation of the TOX3 promoter as a significant contributor of TOX3 upregulation in luminal subtype breast cancer." (PMID 27806084, 2016).
breast carcinoma (continued). "We have confirmed that TOX3 expression is highly up-regulated in luminal breast cancer compared to normal breast tissues or basal-like tumors." (PMID 27806084, 2016). "To examine molecular mechanisms of TOX3 regulation in breast cancer, we investigated both genetic and epigenetic factors using cell lines and datasets derived from primary breast tumors available through The Cancer Genome Atlas (TCGA)." (PMID 27806084, 2016). "In this study, we tested if overexpression of TOX3 is due to epigenetic factors that regulate TOX3/CASC16 expression in breast cancer cells." (PMID 27806084, 2016). "It is possible that SNPs rs3803662 and rs4784227 modulate CpG island methylation and thus contribute to subtype-specific expression of TOX3 in breast cancer." (PMID 27806084, 2016). "Gene copy number of TOX3 were examined in six breast cancer cell lines, including four luminal breast cancer cells (ZR-75-30, MDA-MB-175VII, HCC-202, and T-47D) and two basal-like breast cancer cells (HCC-70 and HCC-1500)." (PMID 27806084, 2016). "In vitro studies were performed on MCF7, BT474 and MDA-MB-231 cell lines to study the effects of TOX3 modulation on gene expression in the context of breast cancer cells." (PMID 25632947, 2015). "Here we analyzed TOX3 expression in murine and human mammary glands and in molecular subtypes of breast cancer, and assessed its ability to alter the biology of breast cancer cells." (PMID 25632947, 2015). "Since a substantial subset of LumB breast tumors highly expressed TOX3, we sought to correlate TOX3 expression with outcome, using the on-line KM-Plotter for breast cancer." (PMID 25632947, 2015). "Together, this work implicates a role for TOX3 in tumor progression/metastasis as well as modulation of ER-dependent responses, potentially explaining the poorer outcome of the TOX3-high subset of LumB breast cancers." (PMID 25632947, 2015). "Nevertheless, unliganded ER has recently been shown to play a significant role in gene regulation in breast cancer cells, and we would propose that TOX3 plays a modulatory role on this activity." (PMID 25632947, 2015). "In the MCF-7 breast cancer cell line, TOX3 upregulates a subset of ER target genes in addition to genes involved in cell cycle, cancer progression and metastasis." (PMID 25632947, 2015). "Despite this association, little is known concerning the expression pattern or biological functions of TOX3 in breast cancer or in mammary epithelial cells." (PMID 25632947, 2015). "The TOX3 gene was expressed across multiple molecular subtypes of breast cancers, and there was heterogeneity of expression within each subtype." (PMID 25632947, 2015). "Together, these results suggest two different roles for TOX3, one in the initiation of breast cancer, potentially related to expression of TOX3 in mammary epithelial cell progenitors, and another role for this nuclear protein in the progression of cancer." (PMID 25632947, 2015). "Among the disease-associated genomic regions, TOX3 and FGFR2 genes have been identified as breast cancer susceptibility genes in BRCA1/2-wild-type breast cancer patients from Sardinia." (PMID 25956309, 2015). "The TOX3 protein was also highly expressed in a subset of breast cancers, predominantly among histologically defined luminal B (LumB) and LumBHer2+ breast cancer." (PMID 25632947, 2015). "Using MCF-7 cells, we found that TOX3 has the ability to acutely regulate key genes involved in cell cycle and metastases, two key features in breast cancer progression." (PMID 25632947, 2015). "This study indicated the role of TOX3 and FGFR2 as breast cancer susceptibility genes in BRCA1/2-wild-type breast cancer patients from Sardinian population." (PMID 25956309, 2015). "Little is known regarding the expression pattern or biological role of TOX3 in breast cancer or in the mammary gland." (PMID 25632947, 2015).
breast carcinoma (continued). "Analysis of a series of samples from primary breast cancer revealed extreme variability in TOX3 mRNA expression ranging from undetectable to 100-fold over that detected in two normal breast tissue samples." (PMID 25632947, 2015). "Together, these results offer a potential link between breast cancer metastasis and TOX3 expression." (PMID 25632947, 2015). "In the present study, our data suggest that TOX3/LOC643714 rs8051542 and rs4784227 polymorphisms are significantly associated with the breast cancer risk." (PMID 24481062, 2014). "Among them, two single nucleotide polymorphisms (SNPs), rs2046210 at 6q25 and rs4784227 in the TOX3 gene were highlighted for their potential biological contribution to the development of breast cancer." (PMID 25531440, 2014). "The current analyses suggest that 10 loci are now known to be associated with breast cancer risk for BRCA1 mutation carriers: 1q32, 10q25.3, 19p13, 6q25.1, 12p11, TOX3, 2q35, LSP1 and RAD51L1 all reported here and TERT." (PMID 23544013, 2013). "The most significant associations were observed for known breast cancer susceptibility regions, rs2420946 (per allele P = 2×10−14) in FGFR2 and rs3803662 (P = 5.4×10−11) near TOX3." (PMID 23544012, 2013). "Our results support that TOX3 should be further investigated to elucidate its role in breast cancer biology." (PMID 24069272, 2013). "Studies by the Consortium of Investigators of Modifiers of BRCA1/2 (CIMBA) have demonstrated that common alleles in RAD51, FGFR2, MAP3K1, TOX3/TNRC9, LSP1, SLC4A7/NEK10, a 2q35 locus and a 5p12 locus affect breast cancer risk in BRCA2 mutation carriers." (PMID 22513257, 2012). "Knockdown of TOX3 expression with siRNA in the luminal A breast cancer cell line ZR-75-1 increased cellular proliferation." (PMID 23270421, 2012). "Prominent examples are genome-wide association studies which led to the identification of novel breast cancer risk factors such as polymorphisms in FGFR2, CCND1, TOX3, MAP3K1, LSP1, CDKN2A, and 2B." (PMID 23226154, 2012). "With the exception of HBEC1, TOX3 expression was readily detected in all unmethylated samples including normal lung tissue, HBEC2, as well as lung and breast cancer cell lines with unmethylated TOX3 promoter such as H1838 and T47D." (PMID 22496870, 2012). "The promoter CpG islands of TOX and TOX3 were also methylated in 20 and 25% lung, and 75 and 50% breast cancers cell lines, respectively." (PMID 22496870, 2012). "Numerous genome-wide association studies (GWAS) also have identified approximately fifty common genetic loci for breast cancer risk in low penetrance genes such as FGFR2, ESR1, LSP1, MAP3K1, RAD51L1 and TOX3." (PMID 22606018, 2012). "Methylation of TOX was almost exclusively seen in breast cancer, whereas TOX3 methylation was more prevalent in lung than breast cancer." (PMID 22496870, 2012). "In contrast, TOX3 expression was completely silenced in sham (S) lung and breast cancer cell lines with dense promoter methylation such as H1299, SKLU1, H2009, and MDA-MB-231." (PMID 22496870, 2012). "So far, one study showed an effect of TOX3 expression on breast cancer in that increased level of TOX3 mRNA predicted breast cancer metastasis to bone." (PMID 23270421, 2012). "Comparing the ORs for male breast cancer with the published ORs for female breast cancer, three SNPs—rs13387042 (2q35), rs3803662 (TOX3), and rs6504950 (COX11)—showed significant differences in ORs (p<0.05) between sexes." (PMID 21949660, 2011). "Previously identified breast cancer susceptibility loci had the most significant associations among BRCA2 mutation carriers (FGFR2: per allele and TOX3: per allele )." (PMID 21060860, 2010). "Estimates of breast cancer association for loci (two confirmatory loci at FGFR2 and TOX3, and two novel loci with stage 1 and 2 combined of p<10−4) among BRCA2 mutation carriers in a two-staged genome-wide association study." (PMID 21060860, 2010).
breast carcinoma (continued). "Polymorphisms in or near TOX3, LSP1, HCN1, MAP3K1 and at 2q35 are less strongly associated with breast cancer risk than polymorphisms in FGFR2; the increased risks range from 4% to 20% with each risk allele." (PMID 19232126, 2009). "Genome-wide association studies (GWAS) have identified breast cancer susceptibility loci in or near genes such as FGFR2, TOX3 (formerly known as TNRC9), LSP1, HCN1/MRPS30, MAP3K1 and at 2q that had not previously been considered." (PMID 19232126, 2009). "For example, SNPs in TOX3 and CASP8 alter the risk for developing breast cancer, and SNPs in FGFR2 and TOX3 are strongly associated with ER-positive breast cancer." (PMID 19094228, 2008). "TOX3 is an HMG box protein that is involved in chromatin structural modification, and it is one of the low penetrance breast cancer risk genes recently identified in genome-wide association studies." (PMID 19094228, 2008). "However, TOX3 has been shown to stimulate estrogen in ovarian granulosa cells, suggesting a role in breast cancer pathogenesis." (PMID 35267517, 2022). "The role of TOX3 in relation to breast cancer is less clear." (PMID 35267517, 2022). "In addition to breast cancer, TOX3 was also found to be increasingly expressed in tissues of colon cancer and lung adenocarcinoma." (PMID 33716953, 2020). "Therefore, it is worth exploring the role of TOX3 in breast cancer from the perspective of estrogen biosynthesis and function." (PMID 33716953, 2020). "In the present study, we investigated the biological function of TOX3 in estrogen production in ovaries in order to further explain the relationship between TOX3 and breast cancer, using KGN cells, the most commonly used human granulosa cell line, which are capable of estrogen synthesis." (PMID 33716953, 2020). "TOX3 may play dual roles in cancer initiation and progression considering the decreased expression of TOX3 mRNA in breast cancers and increased expression of TOX3 mRNA in metastatic breast cancer." (PMID 32425888, 2020). "This strongly suggests that TOX3 plays an important role in the development of breast cancer; however, whether TOX3 promotes the development of breast cancer through its involvement in the regulation of estrogen synthesis is still unclear." (PMID 33716953, 2020). "Since that, Meyer and Carroll (2012) suggested a tumour suppressor role for TOX3 in breast cancer." (PMID 31338012, 2019). "Thus, in this article, we tried to investigate the association between 16q region including TOX3/LOC643714 locus, which interacts with FOXA1, and breast cancer risk in a cohort of Iranian population." (PMID 31338012, 2019). "TOX3 and FOXA1 proteins are believed to be involved in the susceptibility of breast cancer." (PMID 31338012, 2019). "Previous studies suggest that the rs3803662 risk allele may most strongly increase the likelihood of luminal A tumors in postmenopausal breast cancer, and that expression levels of TOX3 and/or LOC643714 might influence the progression of breast cancer." (PMID 31125336, 2019). "Among them, 28 SNPs are known to be associated with overall breast cancer risk including 3 SNPs already identified to be associated with breast cancer risk in the Tunisian population namely rs1219648, rs2981582 in FGFR2 and rs8051542 in TOX3." (PMID 30594178, 2018). "To determine if de-methylation of the promoter could increase expression of TOX3, we treated a basal-like breast cancer cell line (UACC-3199) with a DNA methylation inhibitor, 5-aza-2’-deoxycytidine (5-aza-CdR)." (PMID 27806084, 2016). "This suggests that methylation of TOX3 may be one of several factors involved in the regulation of TOX3 in breast cancer." (PMID 27806084, 2016). "The study discovered for the first time that three SNPs (rs9933638, rs12443621, and rs3104746) at the TOX3/LOC643714 locus contributed to lung cancer risk, providing new evidences that lung cancer and breast cancer are linked at the molecular and genetic level to a certain extent." (PMID 27486757, 2016).
breast carcinoma (continued). "MCF-7 is an ER+ luminal type breast cancer cell line with low TOX3 expression." (PMID 25632947, 2015). "In addition, TOX3 has the potential to regulate ER target gene expression in the face of limiting concentrations of estrogen, of potential importance in considering therapeutic modalities for TOX3+ breast cancer." (PMID 25632947, 2015). "Together, our data suggest that TOX3 expression within the context of breast cancer is likely a tumor promoter rather than a strict tumor suppressor as had been proposed based on the decrease in TOX3 expression associated with disease risk." (PMID 25632947, 2015). "In order to explore the role of breast cancer susceptibility variants in a Southeast Chinese population, we genotyped two common SNPs at chromosome 6q25 (rs2046210) and in TOX3 (rs4784227) in a case-control study with a total of 702 breast cancer cases and 794 healthy-controls." (PMID 25531440, 2014). "In this case-control study, 623 Chinese female breast cancer patients and 620 cancer-free controls were recruited to investigate the role of five SNPs in TOX3/LOC643714 (rs8051542, rs12443621, rs3803662, rs4784227, and rs3112612); Linkage disequilibrium (LD) pattern analysis was performed." (PMID 24481062, 2014). "Four further genes, FGFR2, LSP1, MAP3K1, and TOX3, were associated with a mild increase in risk of breast cancer in a GWAS; however over 50% of breast cancers occur in women who do not carry these higher risk genotypes." (PMID 23738139, 2013). "A previous study indicated that increased expression of TOX3 could be a predictor of breast cancer metastasis to bone." (PMID 24143190, 2013). "Previously reported BRCA2-modifying alleles for breast cancer, including those in FGFR2, TOX3, MAP3K1, LSP1, 2q35, SLC4A7, 5p12, 1p11.2, ZNF365, and 19p13.1 (ER-negative only), are also associated with breast cancer risk in the general population and/or BRCA1 mutation carriers." (PMID 23544012, 2013). "Although TOX3 falls out of the minimum LOH region, in view of the highly significant association of rs3803662 with breast cancer risk, we hypothesised TOX3 to be a likely candidate tumour-suppressor gene present on the 16q arm." (PMID 24069272, 2013). "However, these assays also revealed dense methylation of TOX3 promoter in some lung and breast cancer cell lines." (PMID 22496870, 2012). "Such function in ER positive breast cancer cells, where TOX3 expression is high, could promote tumour enlargement, invasion of nearby tissues, seeding of lymph nodes which would subsequently shorten the time until death or distant metastasis." (PMID 23270421, 2012). "Consequently, our findings proposed the hypothesis that TOX3 closely correlates with breast cancer development by promoting proliferation and anti-apoptosis of breast tumor cells." (PMID 33716953, 2020). "In the several GWAS, a number of novel genetic variants and loci at the TOX3/LOC643714 locus were identified to be independently associated with elevated risk of breast cancer and rs3803662 was highlighted for its potential biological contribution to the development of breast cancer." (PMID 27486757, 2016). "However, once cell transformation is initiated, TOX3 likely plays a significant role in rendering resulting tumors more aggressive and metastatic, and thus may serve as a novel biomarker for LumB breast cancer." (PMID 25632947, 2015). "Moreover, increased expression of TOX3 was relevant to bone metastasis in breast cancer patients." (PMID 26239137, 2015).